EGFR (epidermal growth factor receptor)
Diseases named in the same sentence as EGFR in open-access papers (continued):
Sharing a sentence is not in itself a finding about the gene and the disease.
tumor (continued). "In SRC, univariate analysis showed that age, tumor size, tumor location, venous tumor emboli, nervous invasion, serosa invasion, lymph node metastasis, TNM stage, and EGFR expression were significant prognostic factors." (PMID 26642199, 2015). "Using the same EGFR-targeted minicell method for delivery, we have shown here that a miR-193a-3p mimic can exert similar control on MPM tumor growth in vivo." (PMID 26125439, 2015). "Another study showed that annexin A8, which is highly expressed in CCs but downregulated upon tumor dedifferentiation, is downregulated by activation of the EGF/EGFR system via PI3K and Akt and that this correlated with EMT in CC cells." (PMID 26729094, 2015). "The first is the activation of the EGFR/PI3K/Akt/mTOR signaling pathway in GBM cells, a key signaling factor in the development of GBM mediating tumor proliferation." (PMID 26110872, 2015). "Comparison of NMR metabolite profiles obtained from control (CALS) and EGFR TKI-resistant (CALR) cells grown as 2D monolayers, 3D spheroids or xenograft tumours in athymic mice revealed a number of differences between the sensitive and drug-resistant models." (PMID 25742484, 2015). "EGFR overexpression and amplification was frequently observed in ESCC and was correlated with advanced tumor stage and poor prognosis." (PMID 26462025, 2015). "In addition we found that, presence of EGFR instead of ErbB2 in the triple oncogene combination potentially drives an early lung metastasis and give unique liver metastasis from same cellular precursor i.e K5+/K19− suggesting the significant effect of an oncogene on pathogenicity of tumor." (PMID 25940703, 2015). "Lapatinib, a clinically approved EGFR/ERBB2 inhibitor, counteracts BCAR4-driven tumor cell growth, a clinical relevant observation." (PMID 26317614, 2015). "Compared with control group, tunicamycin apparently disrupted the expression of EGFR, HER2 and HER3, as well as the MAPK and PI3K/Akt pathways in tumor samples." (PMID 26498681, 2015). "EGFR overexpression is observed in about 40%–80% of NSCLC patients and is related to a low grade of differentiation, increased tumor growth, and high metastatic rate." (PMID 26295387, 2015). "Epidermal growth factor receptor (EGFR) and anaplastic lymphoma kinase (ALK) are the most crucial tumor driver genes in NSCLC." (PMID 25676398, 2015). "Cetuximab (IMC-C225), an anti-EGFR humanized monoclonal antibody, shows multifaceted benefit in HNSCC by blocking proliferation, angiogenesis and metastasis while increasing tumor cell apoptosis." (PMID 25734659, 2015). "As previously reported, EGFR remarkably increased the activity of ERK1/2 and AKT which are involved in the proliferation, anti-apoptosis, and invasion of tumor cells." (PMID 25895031, 2015). "NIR-PIT is effective against EGFR-positive TNBC in a mouse model and results in slowing of tumor growth, prolonged survival." (PMID 26313651, 2015). "A tumor suppressor endogenous protein, MIG-6, is known to suppress EGFR over-expression by binding to the C-lobe of EGFR kinase." (PMID 25885222, 2015). "In a xenograft model of ML-TNBC, treatment with an EGFR-TKI induced MET transition and subsequent tumor regression." (PMID 25973541, 2015). "Intra-tumor heterogeneity was found in the primary tumors of 9 of 19 (47.3%) cancers with HER2, 8 of 17 (47.0%) cancers with CCND1, 5 of 7 (71.4%) cancers with EGFR, and 23 of 27 (85.2%) cancers with MYC amplification." (PMID 25649416, 2015). "For example, miR-7 is a tumor suppressor in malignancies including CRC, which is able to target EGFR." (PMID 26064956, 2015). "The primary tumours from the MCF10CA1a-EGFR-DEL and—GS expressing cells were surgically resected (6 weeks post injection) and the animals monitored for metastasis using bioluminescence of the tumours." (PMID 25969993, 2015).
tumor (continued). "As the lowest tumor concentration of lapatinib (1 μM) equivalent to the untreated state, phosphoryslation of HER2 and EGFR were relatively high compared to baseline, while p-HER3 was relatively low." (PMID 26571496, 2015). "The aberrant activation of EGFR leads to the triggering of downstream signaling cascades, including the Ras/Raf/MEK/ERK, PI3K-AKT and JAK/STAT pathways, which contribute to tumor progression, metastasis and therapeutic resistance." (PMID 25654224, 2015). "Initial evaluation in A549 (wild-type EGFR) and HCC827 (exon 19 deletion EGFR) tumors showed moderate tumor uptake in both models (about or under 1%ID/g from 0–120 min p.i.)." (PMID 26690113, 2015). "In such instances, tumor biopsy specimens might not carry the EGFR gene mutations identified by the serum proteomic classifier because these classifier-constituting peptides/proteins related to EGFR gene mutation status could be derived from different parts of the tumor." (PMID 26047516, 2015). "In the mice injected with EGFR- and EGFR/NEU3- cells, the tumor growth was faster, the latency period was just less than half as long, and the average tumor volume was also greater than that of those received only the NEU3- cells." (PMID 25803810, 2015). "Previously, we have reported that inhibition of these two pathways using panitumumab (anti-EGFR antibody) and ganitumab (anti IGF-1R antibody) enhanced the FaDu tumor response to radiation." (PMID 25355701, 2015). "MiR-145 had been well described to be involved in tumor invasion and progression by targeting c-Myc, AEG-1, EGFR, NUDT1 and OCT4 in LAC15, 16, 17, and acknowledged to be a putative tumor-suppressor miRNA." (PMID 26582602, 2015). "When treated with EGFR and HER2 inhibition, long lasting tumor regression suggested that panHER inhibition will have clinical benefit in such patients." (PMID 25674538, 2015). "EGFR FISH positive cases (scores 5 and 6) were found in 32/160 (20 %) tumours, with high polysomy in 22 (13.8 %) and amplification in 10 (6.3 %)." (PMID 26478746, 2015). "Monoclonal antibodies or small molecule anti-tumor agents targeting the critical carcinogenic molecular hubs, such as VEGF, EGFR and HER-2, have earned appreciation in the anti-cancer treatment and have been adopted by the evidence based clinical guidelines." (PMID 26024373, 2015). "The upregulation and activation of epidermal growth factor receptor (EGFR) and its ligand, transforming growth factor alpha (TGF-α), have been observed in several tumor types." (PMID 25866816, 2015). "Follow up in vivo pre-clinical studies are the focus of future work, and if successful, clinical trials are necessary to further determine the effect of combined suppression of EGFR and c-Met on HCC tumor growth." (PMID 26000702, 2015). "In studies of EC where the prognostic impact of EGFR amplification by FISH has been assessed, there are discordant results, perhaps due to differing scoring criteria and histological tumour subtype." (PMID 26478746, 2015). "Combinatorial therapy with EGFR and IGF-IR inhibitors prevents disease progression by interrupting paracrine interactions between TNBC tumor cells and their microenvironment." (PMID 26258011, 2015). "The epidermal growth factor receptor (EGFR) and the platelet-derived growth factor receptor β (PDGFRβ) are hallmarks in GBM with driving roles in tumor progression." (PMID 26461476, 2015). "Multivariate analysis by the Cox proportional hazard model found that tumor subtype, age, tumor size, venous tumor emboli, nervous invasion, TNM stage, and EGFR expression were independent prognostic factors for all the patients." (PMID 26642199, 2015).
tumor (continued). "In addition, we also found that the basal expression of EGFR was maintained at a stable level when FoxO1/3a were inhibited, which indicated that EGFR could also be mediated by some other transcription factors when FoxO1/3a lose their functions with the activated AKT pathway in tumor cells." (PMID 25654224, 2015). "In particular, however, it is interesting that NEU3 markedly accelerated the tumor growth in volume and shortened the latency period in the mice injected with the EGFR/NEU3 cells compared with those with the EGFR-cells." (PMID 25803810, 2015). "In NSRC, univariate analysis showed that age, tumor size, tumor location, venous tumor emboli, nervous invasion, serosa invasion, lymph node metastasis, TNM stage, and EGFR expression significantly affected prognosis." (PMID 26642199, 2015). "Consistent with a role of inhibiting efflux in elevating tumor concentrations, there was one patient who achieved complete inhibition of HER2, EGFR, and HER3 phosphorylation at a plasma concentration of 1μM (9 μM in tumor)." (PMID 26571496, 2015). "Furthermore, 2 patients with EGFR-mutant NSCLC previously treated with EGFR tyrosine kinase inhibitors also had a second EGFR T790M mutation not previously identified in the FFPE tumor samples, which can plausibly explain why secondary resistance to EGFR targeted therapies occurred." (PMID 25980577, 2015). "Short overall survival (OS) was associated with non-adenocarcinoma tumor type (P = 0.006), poorly differentiated tumors (P = 0.001), advanced-stage tumors (P < 0.001), smoking history (P = 0.008), and wild-type epidermal growth factor receptor (EGFR) (P = 0.008)." (PMID 26253541, 2015). "Several reports noted that EGFR mutations were recognized in 15–20 % of patients with PPC but that the response to EGFR tyrosine kinase receptor inhibitor (TKI) was weak and transient as a consequence of tumor heterogeneity." (PMID 26682906, 2015). "Analysis of intracranial tumor for drug content revealed less than 50 nM HKI-272 in intracranial DBTRG-FL tumor, more than 40-fold less than for subcutaneous tumor, and also less than the in vitro kinase assay IC50 value for this drug against EGFR." (PMID 26023796, 2015). "EGFR and HER2 are the members of the HER family, whose EGF signaling pathway has been shown to play an important role in tumor initiation, progression and metastasis." (PMID 26490766, 2015). "In addition to the direct inhibition of tumor growth, the Fc portions of the therapeutic mAbs, such as the IgG1 portion of the anti-epidermal growth factor receptor (EGFR) mAb cetuximab, might interact with the Fc-gamma receptors (FcγR) on myeloid cells and modulate their suppressive activity." (PMID 26579227, 2015). "Paired samples of tumor and blood were obtained from a total of 18 patients with NSCLC after they had developed resistance to EGFR-TKI treatment, and the mechanisms of resistance were analyzed by digital PCR." (PMID 26334838, 2015). "It has been reported that GST, EGFR and PRKACB are responsible for signal transduction pathways involved in tumor growth and differentiation in different type of cancers." (PMID 25928635, 2015). "While reduced uptake in well-differentiated areas within the tumor could be attributed to reduced accessibility or vascular permeability, the findings reported here are consistent with previous work demonstrating that EGFR loses ligand-binding affinity during maturation and differentiation." (PMID 26120042, 2015). "Because TMC and STIC of U251 differentially expressed EGFR and NOTCH1, we carried out a study on the impact of EFEMP1 on tumor heterogeneity, based on its potential twofold effect in these two different cell subpopulations." (PMID 26307682, 2015). "Ectopic expression of c-Cbl induced growth inhibition and apoptosis as well as EGFR down-regulation in NSCLC cells, confirming the tumor suppressor role of c-Cbl." (PMID 25980579, 2015).
tumor (continued). "EGFR inhibitors, including cetuximab and lapatinab, can dramatically reduce tumor burden in HNSCC animal models or patients In the present study, the EGFR pathway is frequently activated in Tgfbr1/Pten 2cKO mice." (PMID 25723392, 2015). "EGF was found to facilitate DNA synthesis, regeneration, tumour growth and progression of HCC cells, and bind with EGFR as the potential connection between inflammation and HCC and one of therapeutic opportunities 3,10." (PMID 24268047, 2014). "Icotinib blocks EGFR phosphorylation (IC50 = 45 nM) in A431 cell line and inhibits tumor cell proliferation." (PMID 25110867, 2014). "EGFR and VEGFA/B/C expression in human disease pathways play an important regulatory role in tumor angiogenesis, invasion and metastasis." (PMID 23943374, 2014). "Overall, EGFR expression was detected in 14 ACC cases (63.6%), including 6 samples where the tumor cells showed strong staining intensities (3+)." (PMID 24457059, 2014). "In this study, we investigated gene expression and function of Notch1, EGFR and PDGFR to determine their role among GBM tumor core- (c-CSC) vs. peritumor tissue-derived cancer stem cells (p-CSC) of six cases of GBM." (PMID 25380967, 2014). "This higher stabilization of EGFR during RCC development can result in the stimulation of cell proliferation and apoptosis inhibition, favoring migration, invasion and tumor angiogenesis." (PMID 25909813, 2014). "Of the 86 cases examined, we found 43%, 77%, 52% and 92% of the cases to have EGFR, HER-2, HER-3, and HER-4 immunostaining present in >5% of tumour cells respectively." (PMID 24609222, 2014). "Incubating tumour cells with gefitinib or erlotinib led to an increased heterodimerisation of IGF1R and EGFR resulting in a pronounced IGF1R-activation and therefore amplified activation of downstream mediators." (PMID 25444177, 2014). "Using this technology they quantified expression of four signaling proteins involved in GBM (EGFR, PTEN, phospho-Akt and phospho-S6) correlating their results with tumor progression and patient survival." (PMID 24473088, 2014). "According to our results, EGFR GCN is heterogeneous in CRC and the values obtained with IHC guidance from selected tumor areas are higher than the ones obtained by random selection." (PMID 24940619, 2014). "In both the primary tumor and the metastases, Claudin-4 was most frequently expressed, followed by GLUT-1, CAIX, EGFR and IGF1R." (PMID 25417118, 2014). "How Nedd4-1 mediates EGFR cell migration and invasion signaling in both GCA and NSCLC cells is an important question for understanding the role of Nedd4-1 in tumor genesis and progression and needed to investigate further." (PMID 25395181, 2014). "EGFR expression was substantially down-regulated in the CHIPOE compared with the control, whereas CHIP knockdown tumor tissues showed an up-regulated expression of EGFR in the membranes." (PMID 24722501, 2014). "Since the two oligopeptides specific for EGFR and HER2 were involved in the fusion protein Ec-LDP-Hr-AE, it was likely bound to tumor cells overexpressing both receptors instead of normal cells with low expression of one or both receptors." (PMID 24664246, 2014). "EGFR-related downstream effects are mediated by the phosphatidylinositol 3-kinase (PI3K) - Akt signaling cascade, which promotes tumor cell growth and inhibition of apoptosis by activation of mTOR." (PMID 24593867, 2014). "Both exogenous IL-6 and TGF-β induced EGFR inhibitor resistance and endogenous TGF-β was produced from EGFR inhibitor resistant tumor cells." (PMID 25240937, 2014). "Biological effects on tumor cells were studied in patients with metastatic cancers over-expressing HER2 and EGFR." (PMID 25110867, 2014).
tumor (continued). "The prognostic value of EGFR and its downstream signaling molecules such as STAT3 and ERK1 have been studied in many tumor types." (PMID 25146150, 2014). "At the end of the study, tumor microvasculature was observed under confocal microscope, and immunohistochemical analyses were performed to detect CD31, VEGF, COX-2, and EGFR." (PMID 24860830, 2014). "Taken together, our results suggested that miR-7 inhibited tumor metastasis and reversed EMT through AKT and ERK1/2 pathway inactivation by reducing EGFR expression in EOC cell lines." (PMID 24816687, 2014). "Additional IHC analysis confirmed a significant increase of E-cadherin, EGFR and CD133 signals and reduced expression of Nestin protein in xenograft tumor samples belonging to PANC-1 shSMAD4 tumors as compared with the control group." (PMID 24625091, 2014). "Considering all the patients showing downregulation of total HER4 in their tumor tissue, in 82% of these NRG4 was also downregulation and in 86% one or more of the EGFR-shared ligands (HB-EGF, epiregulin, betacellulin) was upregulated." (PMID 24728052, 2014). "Several organ- or tumor-specific markers, including CEA, EGFR, PSA, HER-2, and MUC-1, have also been applied in antibody-based detection and isolation of CTCs." (PMID 25521853, 2014). "To further explain the relationship between EGFR expression in CK-negative CTCs and EMT process we developed an experimental model using MCF-7 tumor cells." (PMID 25277187, 2014). "Especially decorin has a recognized regulatory role in tumour development, most notably via its ability to down regulate several members of the receptor tyrosine kinase (RTK) family members such as the epidermal growth factor receptor (EGFR)." (PMID 26056582, 2014). "The leucine rich repeats and immunoglobulin-like protein 1 (LRIG1) is a newly discovered negative regulator of epidermal growth factor receptor (EGFR) and a proposed tumor suppressor." (PMID 24709893, 2014). "The mice were sacrificed 42 days after implantation and the tumors were removed to monitor the tumor sizes and to determine RBM5 and EGFR expression by RT-qPCR and Western blot analysis." (PMID 25441176, 2014). "It has been demonstrated that EGFR-TKIs competitively bound with EGFR and blocked several downstream signaling pathways including PI3K/Akt and MARK/Erk, resulted in inhibition of tumor cell proliferation, tumor vascularization and metastasis." (PMID 25474307, 2014). "We confirmed the contribution of EGFR and HER2 activation in NTS induced tumor growth by treating xenografted mice with NTS-h and lapatinib." (PMID 25249538, 2014). "Malignant tissue with proliferative potential presented EGFR overexpression and inverse downregulation of LRIG1, consistent with LRIG1 being a suppressor of neoplastic transformation by counteracting the tumor growth property of EGFR." (PMID 24709893, 2014). "CI-1033 was evaluated for its ability to inhibit tumor formation in esophageal squamous cell carcinoma (TT, TE2, TE6, TE10 cell lines) in vitro and in vivo with EGFR and HER2 overexpression in all four cell lines." (PMID 25251190, 2014). "MK2206, as well as PI3K inhibitors, have been shown to act synergistically to improve anti-tumor activity in combination with EGFR TKIs in both the KRAS/EGFR WT and EGFR M+ NSCLC setting." (PMID 24946858, 2014). "The HE4 participation in promoting the neoplastic tumor growth was also demonstrated by other authors, they demonstrated that the HE4 expression in cancer cells is associated with greater adhesion, migration and proliferation which may be dependent on the EGFR-MAPK cascade." (PMID 25018782, 2014).